IGLV4-3 (immunoglobulin lambda variable 4-3)
Description:
V region of the variable domain of immunoglobulin light chains that participates in the antigen recognition. Immunoglobulins, also known as antibodies, are membrane-bound or secreted glycoproteins produced by B lymphocytes. In the recognition phase of humoral immunity, the membrane-bound immunoglobulins serve as receptors which, upon binding of a specific antigen, trigger the clonal expansion and differentiation of B lymphocytes into immunoglobulins-secreting plasma cells. Secreted immunoglobulins mediate the effector phase of humoral immunity, which results in the elimination of bound antigens. The antigen binding site is formed by the variable domain of one heavy chain, together with that of its associated light chain. Thus, each immunoglobulin has two antigen binding sites with remarkable affinity for a particular antigen. The variable domains are assembled by a process called V-(D)-J rearrangement and can then be subjected to somatic hypermutations which, after exposure to antigen and selection, allow affinity maturation for a particular antigen.
Synonyms: IGLV43; V5-1
Gene: Immunoglobulin variable (V) gene on chromosome 22 (22,871,507 to 22,872,035, forward strand). Ensembl gene ENSG00000211672.
Subcellular location: Secreted; Cell membrane
Gene Ontology:
Biological process: immune response
Cellular component: extracellular region; immunoglobulin complex; plasma membrane
Homologues: Orthologues: macaque IGLV4-3 (89% identical), mouse Iglv3 (59% identical). Paralogues in human: IGLV4-69 (60% identical), IGLV4-60 (57% identical), IGLV9-49 (54% identical), IGLV5-45 (47% identical), IGLV5-37 (46% identical), IGLV5-52 (45% identical), IGLV11-55 (40% identical), IGLV2-8 (40% identical), IGLV2-18 (39% identical), VPREB1 (39% identical), IGLV1-44 (39% identical), IGLV1-50 (39% identical), and 81 more.